PIK3CA (phosphatidylinositol-4,5-bisphosphate 3-kinase catalytic subunit alpha)
Diseases named in the same sentence as PIK3CA in open-access papers (continued):
Sharing a sentence is not in itself a finding about the gene and the disease.
cervical carcinoma (continued). "This suggests that PIK3CA mutations may have an important role in the development of HPV+ HNSCC as it has been hypothesized for cervical cancers." (PMID 27043631, 2016). "We have previously shown that patients with early stage cervical cancer (IB/II) with PIK3CA exon 9 or 20 mutations treated with radical RT in combination with cisplatin had significantly worse outcome than those whose tumours expressed PIK3CA-WT." (PMID 27489350, 2016). "Previously we showed that a subset of cervical cancer patients with PIK3CA exon 9 or 20 mutations had significantly worse clinical outcomes after radiation therapy (RT) and cisplatin chemotherapy than patients whose tumours expressed wild-type PIK3CA." (PMID 27489350, 2016). "In addition, the histological subtype can serve as another predictor for PIK3CA mutation in cervical cancer." (PMID 26358014, 2015). "Therefore, in this study, we investigated the clinicopathological and prognostic relevance of PIK3CA mutations in a large cohort of Chinese patients with surgically resected cervical cancer." (PMID 26358014, 2015). "Genes involved in the PI3K pathway represent potential therapeutic targets for cancers, and PIK3CA mutation status may be useful as a biomarker for targeted therapy of cervical cancer." (PMID 26358014, 2015). "Furthermore, the presence of a PIK3CA mutation specifically correlated with advanced age at disease onset in SCC in this Dutch cervical cancer cohort." (PMID 26197069, 2015). "The mutation status in the PIK3CA gene could be used as a targeted biomarker for cervical cancer patients." (PMID 26358014, 2015). "Further investigations are warranted to confirm whether PI3K pathway inhibitors could improve radiotherapy efficacy in cervical cancer patients who have PIK3CA or PTEN mutations." (PMID 25669975, 2015). "Indeed, IHC for PIK3CA expression in cervical intraepithelial neoplasia has been shown possessing diagnostic significance for cervical cancer." (PMID 24511546, 2014). "In addition to mutations, genomic amplification of PIK3CA has been reported in various human cancers, including ovarian cancer, cervical cancer, thyroid cancer, and non-small cell lung cancer (NSCLC)." (PMID 22292935, 2012). "These evidences supported that PIK3CA is an oncogene in cervical cancer and PIK3CA amplification may be linked to cervical tumorigenesis." (PMID 19384426, 2007). "In-depth analysis of the PIK3CA mutation landscape in our cohort revealed that all alterations were restricted to canonical helical domain hotspots—E542K and E545K—which are among the most frequently reported oncogenic mutations in solid tumors, including cervical cancer." (PMID 40726978, 2025). "Therefore, PIK3CA mutations not only serve as indicators of cervical cancer onset but also may suggest a heightened risk for splenic metastasis." (PMID 41040533, 2025). "However, there is disagreement as to whether the PIK3CA mutation status correlates with patient survival in cervical cancer in previous reports." (PMID 34203201, 2021). "The prevalence of PIK3CA mutations in this study cohort was in line with that reported in previous landmark studies using whole exome sequencing to analyze tumor-blood pairs obtained from patients with cervical cancer, suggesting that the analytical pipeline employed in the present study is robust." (PMID 35008475, 2021).
cervical carcinoma (continued). "Taken together, PIK3CA alterations, including mutations and amplification, may be a good marker to predict tumor progression and chemotherapy resistance, possibly providing a novel concept in the treatment of advanced cervical cancer." (PMID 31295843, 2019). "Our observations suggest that molecular inhibitors targeting the PI3-kinase/Akt pathway may improve the outcome by CCRT in cervical cancers harboring PIK3CA mutation, providing significant implications for novel treatment strategy based on precision medicine in the disease." (PMID 30075505, 2018). "To validate the relationship between miR-29a and PIK3CA in clinical settings, we examined data from the TCGA dataset and found that cervical cancer patients generally exhibited a higher expression of PIK3CA and lower expression of miR-29a." (PMID 39590348, 2024). "The reduced expression of PIK3CA, mediated by miR-29a, led to a decrease in the proliferation, division, erosion, and metastasis of cervical cancer cells, which was confirmed through wound healing and cell migration assays." (PMID 39590348, 2024). "Similar findings have also been obtained from one deliberate investigation conducted in cervical squamous cell carcinoma (CESC), where PIK3CA-mutant cervical cancer cells were more sensitive to the combination of BYL719 and cisplatin in vivo." (PMID 38616230, 2024). "PIK3CA mutations induce the β-catenin/SIRT3 signaling pathway thereby promoting glycolysis and proliferation of cervical cancer cells, thereby accelerating cancer progression." (PMID 38706901, 2024). "It provides a new paradigm for diagnosing cervical cancer by examining the miR-29a and PIK3CA expression in actual patients." (PMID 39590348, 2024). "This study aims to investigate the effects of miR-29a on cervical cancer cell survival, migration, and proliferation, specifically focusing on its ability to inhibit PIK3CA." (PMID 39590348, 2024). "In cervical cancer, the phosphatidylinositol 3-kinase catalytic subunit alpha (PIK3CA) gene is a critical oncogene." (PMID 39590348, 2024). "Our study aims to directly target the expression of PIK3CA to treat cervical cancer and inhibit tumor progression." (PMID 39590348, 2024). "We observed that the expression of PIK3CA varied depending on the cervical cancer profile, and this variation was mirrored by the miR-29a expression levels." (PMID 39590348, 2024). "In Patient 1, mutations in maternal ctDNA sample at baseline were discovered, including the most common genes in cervical cancer PIK3CA, PTEN, and MAPK1." (PMID 39506833, 2024). "By targeting PIK3CA using miR-29a, we hope to offer a novel therapeutic strategy for treating advanced cervical cancer." (PMID 39590348, 2024). "It demonstrated a good efficacy in PIK3CA-altered solid tumors, especially in cervical cancer, from the first-in-human study of Alpelisib." (PMID 38253702, 2024). "PIK3CA is frequently mutated in cervical cancer and in HPV-positive HNSCC and is associated with a poorer prognosis than cancers with wild-type PIK3CA." (PMID 38535531, 2024). "In cervical cancer, genomic alterations in PIK3CA are the most common (26%), followed by EP300 (11%) and FBXW7 (11%)." (PMID 38201563, 2023). "Tian et al30 identified that the cervical cancer patients with five notable nonsynonymous mutant genes (PIK3CA, BRAF, GNA11, FBXW7, and CDH1) metastatic relapse significantly mutated mutations had significantly poor DFS and OS." (PMID 35762423, 2023).
cervical carcinoma (continued). "Around 28.57 % of HPV-negative cervical cancer patients were positive for PIK3CA mutation, and 4.76 % tested positive for this mutation among the HPV-positive cervical cancer patients." (PMID 35795639, 2022). "Along this line, overexpression of miR-202-5p in cervical cancer reduced PIK3CA gene expression as well as the activation of PI3K/AKT/mTOR signaling pathway, which suppressed proliferation, invasion, and EMT." (PMID 35682549, 2022). "By comparing with the ONCOKB database, the role of PIK3CA in cervical cancer was further highlighted, especially for E545K and E542K." (PMID 35205332, 2022). "Noteworthy, a very recent paper demonstrated that PIK3CA expressing cervical cancers demonstrated an increase in the MDSC and M2 inhibitory myeloid populations." (PMID 36010260, 2022). "PIK3CA mutation is associated with poor treatment response and low survival rate, while MDM2 is associated with the development of cervical cancer and poor prognosis." (PMID 35795639, 2022). "In our study, the PIK3CA, KMT2C, KMT2D, LRP1B, and FBXW7 genes were the five genes with the highest mutation frequencies in cervical cancer samples, which is mostly consistent with the results in TCGA." (PMID 36333792, 2022). "In fact, a recent report indicated that PIK3CA mutations promote glycolysis and proliferation by inducing the β-catenin/SIRT3 axis in cervical cancer." (PMID 36091047, 2022). "PIK3CA and MTOR were the most frequently mutated genes, demonstrating that the PI3K/Akt/mTOR signaling pathway is commonly activated in cervical cancer." (PMID 35205332, 2022). "This multigene NGS analysis revealed several novel genetic alterations in Chinese patients with cervical cancer and highlighted the role of PIK3CA in cervical cancer." (PMID 35205332, 2022). "PIK3CA-E545K is reported to confer resistance to ionizing radiation in cervical cancer cells by inducing overexpression and nuclear accumulation of β-catenin." (PMID 34737943, 2021). "Along similar lines, PIK3CA is reported as the most frequently mutated oncogene in cervical cancer associated with HPV infection, and PIK3CA mutation is the only variable significantly associated with disease recurrence." (PMID 34925445, 2021). "As it physically bound itself to Y-box binding protein 1 (YBX1), recruited YBX1 to the PIK3CA promoter, and it mediated the anti-cancer effects of baicalein in cervical cancer via activating PI3K/Akt pathway." (PMID 34680171, 2021). "For example, PIK3CA was an inclusion criterion in one clinical trial (NCT02957266) for directing cervical carcinoma therapy, as well as, ERBB3 and FBXW7 were considered as biomarkers in several clinical trials for malignant solid tumor." (PMID 34221990, 2021). "The PIK3CA gene, involved in the PI3K signaling pathway, is mutated in 13–36% of the cervical cancer cases, which is why it would be a good potential drug target." (PMID 33926008, 2021). "PIK3CA was considered the most prominent mutant gene in cervical adenocarcinoma, consistent with previous studies on cervical cancer." (PMID 33398034, 2021). "PIK3CA was frequently altered in various cancer types, with the highest clonality present in breast and cervical cancer." (PMID 33397889, 2021). "Whole-exome sequencing of cervical carcinoma results confirmed that the ERBB2/PIK3CA/AKT/mTOR pathway was one of the major mechanisms of cervical cancer in tumorigenesis." (PMID 35070983, 2021). "About 15% of cervical cancers bear amplifications of PIK3CA as part of a commonly amplified locus at 3q26-28." (PMID 33435133, 2021). "Activating mutation of PIK3CA and the resulting activation of PI3K is frequently observed in both uterine endometrial and cervical cancer, and, thus, PI3K-inhibition has been regarded as promising treatment." (PMID 33946532, 2021).
cervical carcinoma (continued). "Accumulating studies have identified various genomic mutations of PIK3CA, EP300, FBXW7, PTEN, HLA-A, ARID1A and so on in different cervical cancer tissues." (PMID 32123519, 2020). "PIK3CA mutation is associated with poor treatment response and low survival rate while MDM2 is associated with tumorigenesis and poor prognosis in cervical cancer." (PMID 31350972, 2019). "In cervical cancer, PIK3CA (33.3%), PD1 (26.7%), and EGFR (20%) were most common, whereas PD1 (40%) was most common in vulvar cancers." (PMID 30848097, 2019). "Mutations in PIK3CA are amongst the most frequently detected mutations in cervical cancer, but other alterations that result in the aberrant PI3K/AKT/mTOR activation, for instance genomic amplifications of PIK3CA or the loss of PTEN, are also reported." (PMID 31058807, 2019). "Additional analysis for PIK3CA in different stages of cervical cancer obtained from an available clinical information dataset, GSE9750, indicated that high PIK3CA amplification was significantly associated with advanced stages in cervical cancer (p < 0.05)." (PMID 31295843, 2019). "Cervical cancer patients with mutant PIK3CA (E542K and E545K) exhibited a higher SUVmax value than those with wild-type PIK3CA (P = 0.037), which was confirmed in xenograft models." (PMID 30547809, 2018). "Meanwhile, the mutation frequency of CHEK1, RASSF1A, EI24, PIK3CA, and LOH11CR2A increased to 51% 107, 50% 108, 41% 107, 37.1% 105, and 36% 107 in cervical cancers, respectively." (PMID 30589505, 2018). "We analyzed DNA sequences on exons 9 and 20 of the PIK3CA gene in archival FFPE biopsy specimens before treatment by direct sequencing in 59 patients with stage IIB to IVA cervical carcinomas treated by CCRT with weekly cisplatin." (PMID 30075505, 2018). "In this study, only patients with early-stage cervical cancer were included, and amplification of PIK3CA was detected in one patient." (PMID 30046040, 2018). "In any case, the current findings further support the significance of PIK3CA genetic aberrations on outcome of cervical cancers treated by CCRT." (PMID 30075505, 2018). "In the present study, we found that the level of glucose metabolism in cervical cancer patients with mutant PIK3CA was dramatically higher than that of patients with wild-type PIK3CA based on the increased SUVmax value detected by 18F-FDG PET/CT." (PMID 30547809, 2018). "In conclusion, we have demonstrated here that PIK3CA mutation is a significant prognostic factor for poor OS and CSS in cervical cancers treated by CCRT with weekly cisplatin." (PMID 30075505, 2018). "Altogether, these results suggest that β-catenin is a vital molecule involved in regulating proliferation and glucose metabolism in cervical cancer cells with mutant PIK3CA." (PMID 30547809, 2018). "Taken together, PIK3CA E542K and E545K mutations promote glucose metabolism and proliferation by inducing the AKT/GSK3β/β-catenin in cervical cancer cells." (PMID 30547809, 2018). "Despite the ethnic and geographic differences, alterations in PIK3CA, followed by FBXW7, were the most common mutations in the various cervical cancer studies." (PMID 27998038, 2017). "Taken together, these data strongly indicate that PIK3CA-mutant cervical cancer cells in which BKM120-induced cytoprotective autophagy occurs respond to the combined inhibition of both PI3K and autophagy." (PMID 28036259, 2017).
cervical carcinoma (continued). "These pathways and the recurrently mutated genes involved therein, such as EP300, ARID1A, FBXW7, NFE2L2, PIK3CA, and ERBB2, were all found to be pathogenic in previous cervical cancer studies." (PMID 28390392, 2017). "In this study, we found that autophagy inhibition enhances the efficacy of a PI3K inhibitor depending on PIK3CA-mutant cervical cancer cell type." (PMID 28036259, 2017). "Here we show that the CaSki cervical cancer cell line that is heterozygous for PIK3CA-E545K, is significantly more resistant to cisplatin than SiHa and HeLa that express PIK3CA-WT." (PMID 27489350, 2016). "Together, these data strongly suggest that expression of PIK3CA-E545K in cervical cancer cells confers resistance to cisplatin and cisplatin plus IR treatment but not IR alone." (PMID 27489350, 2016). "We also show that cervical cancer cells expressing PIK3CA-E545K have a more migratory phenotype than cervical cancer cells expressing PIK3CA-WT and this phenotype is also reversed by GDC-0941." (PMID 27489350, 2016). "Our results show that cervical cancer cells expressing PIK3CA-E545K are more resistant to cisplatin or cisplatin in combination with ionizing radiation (IR) than cells expressing PIK3CA-WT." (PMID 27489350, 2016). "Activating PIK3CA (E545K, E542K) and inactivating PTEN (R233*) mutations were identified in human cervical cancer." (PMID 24705275, 2014). "An interesting difference can be observed when comparing PIK3CA distribution between cervical cancers and the other tumour types." (PMID 24671188, 2014). "Our preliminary studies based on Sequenom assays confirm that PIK3CA and PTEN genes are mutated in cervical cancer patients with poor progression free survival after standard chemoradiation." (PMID 24705275, 2014). "The previous studies have shown that PIK3CA, as a subunit of PI3K, is frequently mutated in various human cancers, such as ovarian, thyroid cancer, breast, cervical cancers, and pituitary tumors." (PMID 22292935, 2012). "A subset of cervical carcinomas was also analysed for PIK3CA protein expression using immunohistochemistry." (PMID 21663621, 2011). "In this study we experimentally assessed the role of the PI3-kinase pathway and its regulator PIK3CA, which is frequently altered in cervical cancer, in HPV-induced transformation." (PMID 21663621, 2011). "In cervical cancer, a gain of the long arm of chromosome 3, where PIK3CA is located, is often described and suggested to be a compulsory second hit for malignant transformation following an hrHPV infection." (PMID 21663621, 2011). "Cervical carcinomas and ectocervical controls were assessed for PIK3CA mRNA and protein expression by quantitative RT-PCR and immunohistochemical staining, respectively." (PMID 21663621, 2011). "In cervical carcinomas, an increased copy number of PIK3CA was positively correlated with an increase in phosphorylated PKB/AKT, one of the downstream effectors." (PMID 21663621, 2011). "In cervical cancer cell lines harboring amplified PIK3CA, the expression of p110α was increased, and was subsequently associated with high kinase activity." (PMID 19384426, 2007). "Recent studies also found that amplification of the PIK3CA gene accompanied by serine 473 phosphorylation of AKT is common in cervical cancers and it seems to be an independent event to HPV infection." (PMID 17622239, 2007). "Apart from STK11, PIK3CA mutations and YAP1 amplification are prevalent cervical cancer drivers." (PMID 41742943, 2026).